TMEM135 (transmembrane protein 135)
Description:
Involved in mitochondrial metabolism by regulating the balance between mitochondrial fusion and fission. May act as a regulator of mitochondrial fission that promotes DNM1L-dependent fission through activation of DNM1L. May be involved in peroxisome organization.
Synonyms: PMP52; FLJ22104
Tractability: Antibody: UniProt predicts a signal peptide or a membrane-spanning region. PROTAC: ubiquitination databases record sites on it; its protein half-life has been measured.
Gene: Protein-coding gene on chromosome 11 (87,037,831 to 87,328,824, forward strand). Ensembl gene ENSG00000166575.
Subcellular location: Mitochondrion membrane; Peroxisome membrane
Subcellular location (Human Protein Atlas): Vesicles
Gene Ontology:
Molecular function: protein binding
Biological process: peroxisome organization; fatty acid biosynthetic process; regulation of mitochondrial fission
Cellular component: mitochondrial membrane; peroxisomal membrane; peroxisome; lipid droplet; mitochondrion
Genetic constraint (gnomAD): Loss-of-function variants: 22 observed, 42.29 expected, observed/expected ratio (o/e) 0.52, 90% interval 0.37 to 0.74. The upper end of that interval is the gene's LOEUF score, 0.74, which puts it in group 3 of 6, group 1 being the genes least tolerant of losing a copy. Missense variants: 399 observed, 459.36 expected, observed/expected ratio (o/e) 0.87, 90% interval 0.8 to 0.94. Synonymous variants: 164 observed, 161.77 expected, observed/expected ratio (o/e) 1.01, 90% interval 0.89 to 1.15.
Homologues: Orthologues: chimpanzee TMEM135 (99% identical), macaque TMEM135 (99% identical), dog TMEM135 (96% identical), pig TMEM135 (96% identical), rabbit TMEM135 (96% identical), mouse Tmem135 (92% identical), rat Tmem135 (91% identical), guinea pig TMEM135 (83% identical), tropical clawed frog tmem135 (79% identical), zebrafish tmem135 (75% identical), Drosophila melanogaster CG11737 (31% identical), Drosophila melanogaster CG31259 (30% identical), and 2 more.
Diseases named in the same sentence as TMEM135 in open-access papers:
TMEM135 is named in the same sentence as 21 diseases in open-access papers, as found by Europe PMC text mining. Sharing a sentence is not in itself a finding about the gene and the disease. The quoted sentences say what the papers report.
age-related macular degeneration (2 papers, 2022 to 2024). Age-related loss of vision in the central portion of the retina (macula), secondary to retinal degeneration. "The discovery of Tmem135 as a gene implicated in retinal aging of mammals lead to subsequent studies on the function of Tmem135 in cells and mice as well as associations between the pathways affected by Tmem135 and age-related retinal diseases such as age-related macular degeneration (AMD)." (PMID 38576540, 2024). "Since mutant Tmem135 mice have similar ocular pathologies as human age-related macular degeneration (AMD) eyes, we compared our homozygous Tmem135 mutant eyecup RNA-Seq dataset with transcriptomic datasets of human AMD donor eyes." (PMID 35031662, 2022).
breast carcinoma (2 papers, 2011 to 2021). "In humans, TMEM135 was identified as an apoptosis-regulating protein in BRCA1-mutant estrogen receptor-positive breast cancer." (PMID 34359920, 2021). "The A allele of rs13387042 (2q35) was significantly associated with contralateral breast cancer in ER negative first tumors while the A allele of rs11235127 (near TMEM135) was significantly associated with contralateral breast cancer in ER positive first tumors." (PMID 22087758, 2011).
Insulin resistance (2 papers, 2023 to 2024). Increased resistance towards insulin, that is, diminished effectiveness of insulin in reducing blood glucose levels. "Conversely, TMEM135 overexpression promotes mitochondrial division, counteracts obesity and insulin resistance, and rescues thermogenesis in peroxisome-deficient mice." (PMID 37773161, 2023). "Most recently, adipose-specific deletion of Tmem135 was shown to result in impaired thermogenesis and increased diet-induced obesity and insulin resistance in mice, revealing significant roles of TMEM135 in the brown fat and energy homeostasis." (PMID 38576540, 2024). "Conversely, Tmem135 overexpression increased thermogenesis and prevented diet-induced obesity and insulin resistance." (PMID 38576540, 2024). "Conversely, TMEM135 overexpression promotes mitochondrial fragmentation, protects against diet-induced obesity and insulin resistance, and rescues thermogenesis in Pex16-AKO mice." (PMID 37773161, 2023). "Assessment of glucose homeostasis in these animals revealed that the TMEM135 knockout results in glucose intolerance, hyperinsulinemia and insulin resistance." (PMID 37773161, 2023). "Adipose-specific TMEM135 knockout in mice blocks mitochondrial fission, impairs thermogenesis, and increases diet-induced obesity and insulin resistance." (PMID 37773161, 2023). "Adipose-specific knockout of TMEM135 in mice blocks cold-induced BAT mitochondrial fission, impairs thermogenesis, and increases high fat diet-induced obesity and insulin resistance." (PMID 37773161, 2023). "Moreover, adipose-specific knockout of TMEM135 results in insulin resistance, independent of its effect on body weight." (PMID 37773161, 2023). "However, despite the lack of difference in body weight, HFD-fed Tmem135-AKO male mice exhibited glucose intolerance and insulin resistance, suggesting that adipose-specific TMEM135 inactivation has a primary effect on insulin sensitivity, independent of body weight difference." (PMID 37773161, 2023).
lung adenocarcinoma (2 papers, 2008 to 2010). A carcinoma that arises from the lung and is characterized by the presence of malignant glandular epithelial cells. "Finally, we have also investigated the role of TMEM135, a gene previously identified in a human lung adenocarcinoma cell line cDNA library in osteogenesis." (PMID 18637193, 2008).
Obesity (2 papers, 2023 to 2024). Accumulation of substantial excess body fat. "Our studies identify brown fat TMEM135 as an important regulator of energy balance and whole-body glucose homeostasis that protects against diet-induced obesity and decreases risk for type 2 diabetes." (PMID 37773161, 2023). "Histologic examination showed that TMEM135 overexpression results in markedly smaller adipocytes in the iWAT depot and a striking protection against obesity-associated whitening of BAT." (PMID 37773161, 2023). "Suggesting translational relevance to metabolic homeostasis in humans, Tmem135 gene expression is decreased in subcutaneous white adipose tissue (WAT) of individuals with obesity." (PMID 37773161, 2023). "Conversely, adipose-specific knockout of TMEM135, which impairs thermogenesis, increases obesity in HFD-fed mice." (PMID 37773161, 2023). "Consistent with its role in promoting thermogenesis, TMEM135 overexpression decreases diet-induced obesity." (PMID 37773161, 2023). "Our studies in human brown adipocytes indicate that this variant is a loss-of-function mutant that impairs mitochondrial fission, suggesting that the increased diet-induced obesity in Tmem135-AKO mice is likely related to a defect in brown fat mitochondrial dynamics and thermogenesis." (PMID 37773161, 2023). "Suggesting that TMEM135 might be relevant to obesity in humans, analysis of publicly available transcriptome-profiling data (GEO: GSE94753) indicates that Tmem135 gene expression is significantly decreased in abdominal subcutaneous WAT of female subjects with obesity as compared to lean individuals." (PMID 37773161, 2023). "Beyond providing a mechanistic insight into the role of TMEM135 in mitochondrial fission, our studies identify TMEM135 as a potential target for therapeutic activation of BAT, perhaps leading to an alternative treatment option for obesity and type 2 diabetes." (PMID 37773161, 2023).
Alzheimer disease (1 paper, 2020). A progressive, neurodegenerative disease characterized by loss of function and death of nerve cells in several areas of the brain leading to loss of cognitive function such as memory and language. "Genes identified by our method suggest putative roles of several biological processes in Alzheimer’s disease, including mitochondrial dysfunction (indicated by UQCR11, MTCH2 and TMEM135), cholesterol transportation (indicated by TMEM135 and OSBP), and neuron activity (indicated by ADRA1A)." (PMID 33137096, 2020).
cardiac hypertrophy (1 paper, 2018). "Mfn1/Mfn2 deficient mice and Tmem135 TG mice show cardiac hypertrophy while mice with induced processing of OPA1 develop dilated cardiomyopathy." (PMID 30102730, 2018). "We observed that the Tmem135 TG heart had significantly increased collagen compared to the WT heart at 6 months of age (n = 4 WT, n = 4 TG, p<0.05 by t-test) indicating increased fibrosis, which is often associated with cardiac hypertrophy." (PMID 30102730, 2018).
deafness (1 paper, 2023). An inherited or acquired condition characterized by the complete loss of the ability to hear from one or both ears. "Defects in the 30 shared genes are related to several pathologies, such as vision abnormalities (TMEM135), cancer (CDH6, FZD10, TIAM2), neuropsychiatric disorders (Tenm4, Pde4dip, Grid2), deafness (TFB1M), neutrophil disorders (VPS45) and others." (PMID 36902345, 2023).
hypertrophic cardiomyopathy (1 paper, 2018). A condition in which the myocardium is hypertrophied without an obvious cause. "Pathologies in the Tmem135 TG heart including hypertrophic cardiomyopathy and collagen accumulation indicative of fibrosis are also observed in the aging heart." (PMID 30102730, 2018).
Hypoinsulinemia (1 paper, 2023). A decreased concentration of insulin in the blood. "Accordingly, HFD-fed Tmem135TG mice exhibited a marked improvement in glucose tolerance in the context of hypoinsulinemia and increased circulating adiponectin levels, suggesting that TMEM135 promotes insulin sensitivity." (PMID 37773161, 2023).
insulinoma (1 paper, 2023). "Moreover, shRNA-mediated knockdown of TMEM135 in MIN6 mouse insulinoma cells or H9C2 rat cardiomyocytes promoted the formation of elongated mitochondria." (PMID 37773161, 2023).
macular degeneration (1 paper, 2021). Loss of vision in the central portion of the retina (macula), secondary to retinal degeneration. "In mice, the pathogenic FUN25 mutation in TMEM135 was associated with age-dependent pathologies, including accelerated retinal aging reminiscent of human macular degeneration; however, mutations in human TMEM135 have not been reported in macular degeneration patients." (PMID 34359920, 2021).
steatosis (1 paper, 2018). Increased lipid within the cytoplasm of cells. "More specifically, perturbation in endoplasmic reticulum and vesicles through the genes MUL1, TMEM135, OSBPL9, SCD1, SREBP-1C, GPAT3 can lead to steatosis." (PMID 30279702, 2018).
metabolic disease (2 papers, 2023 to 2024). A congenital disorder (due to inherited enzyme abnormality) or acquired (due to failure of a metabolically important organ) disorder resulting from an abnormal metabolic process. "There have been published associations with TMEM135 and other human medical conditions such as osteoporosis, breast cancer, prostate cancer, melanoma, non-small lung cancer, glioblastoma multiforme, non-alcoholic fatty liver disease, cognitive disorders, and metabolic disease." (PMID 38576540, 2024). "Using Tmem135 mutant mice, we also validated the protective effect of increased peroxisomes and peroxisomal beta-oxidation on the metabolic disease phenotypes of leptin mutant mice which has been observed in previous studies." (PMID 36599953, 2023). "Functional studies indicated that this specific SNP in TMEM135 reduces the function of the protein and may promote the occurrence of human metabolic diseases." (PMID 38576540, 2024). "Together, these phenotypic changes suggest that impairment of TMEM135 function affects molecular pathways involved in the pathogenesis of metabolic disease with dysregulated lipid metabolism, which may include activation of PPAR signaling and increased peroxisome proliferation." (PMID 38576540, 2024).
TMEM135 also shares sentences with these, for which no sentence is quoted: cancer (2 papers); dilated cardiomyopathy (1); Glucose intolerance (1); Hyperinsulinemia (1); osteoporosis (1); prostate carcinoma (1); type 2 diabetes (1).